VDR (vitamin D receptor)
Diseases named in the same sentence as VDR in open-access papers (continued):
Sharing a sentence is not in itself a finding about the gene and the disease.
vitamin D deficiency (continued). "In this study, our aims are to determine whether vitamin D deficiency is associated with collateralization and whether the FokI polymorphism of the VDR gene could affect collateralization in CAD patients." (PMID 24729966, 2014). "The impact of debilitating variants on VDR function could be exacerbated by vitamin D deficiency or, alternatively, reduced by adequate vitamin D production or intake." (PMID 23805323, 2013). "We determined the prevalence of vitamin D deficiency in girls from South Brazil and investigated whether the genotypic distribution of the BsmI, ApaI and TaqI polymorphisms of the VDR gene and their haplotypes were associated with vitamin D levels." (PMID 22681928, 2012). "Given the high prevalence of vitamin D deficiency in children and adolescents described earlier, it may be speculated that VDR gene polymorphisms could be linked to higher susceptibility to develop vitamin D deficiency." (PMID 22681928, 2012). "Threshold for vitamin D deficiency determining clinical and immunological effect may differ according to evolutionary selection in human populations for VDR gene and for VDREs present in the human genome." (PMID 22848563, 2012). "In our study, NGF down-regulation was observed when VDR was silenced; this may provide a molecular explanation for previous in vivo results demonstrating that animals exposed to transient-early vitamin D deficiency had reduced NGF protein levels." (PMID 21408608, 2011). "We hypothesize that low availability of 1,25-dihydroxyvitamin D, either due to vitamin D deficiency or due to polymorphisms in the vitamin D receptor or in its activating/inactivating enzymes, contributes to the appearance of IRIS." (PMID 19383117, 2009). "Additionally, future trials may benefit from focusing on subpopulations with profound vitamin D deficiency or specific genetic variants related to the VDR, which may modulate the immune response to Mycobacterium tuberculosis." (PMID 40613553, 2025). "In contrast, in men, vitamin D deficiency is more frequently associated with an increased risk of hypertension and endothelial dysfunction, which may result from different hormonal regulation and lower VDR expression levels." (PMID 40871724, 2025). "Interestingly, this study also noted higher serum vitamin D in ASD vs. controls (contrary to most others), positing that VDR dysfunction might lead to functional vitamin D deficiency even if levels appear sufficient." (PMID 40362647, 2025). "This decrease in blood calcium levels among MHD patients could be attributed to various factors, including vitamin D deficiency, hypothyroidism, and the usage of calcium-containing phosphorus binders, vitamin D receptor agonists, and calcium-sensitive receptor agonists." (PMID 40950978, 2025). "Given the central role of VDR in calcium homeostasis and immune regulation, such interactions may have broader clinical implications, particularly in the personalized management of vitamin D deficiency." (PMID 40710009, 2025). "Notably, recent research further reveals that genetic variations in the vitamin D receptor (VDR) pathway can modulate DFU risk: specific VDR single nucleotide polymorphisms (SNPs) may amplify the susceptibility to DFU in individuals with vitamin D deficiency." (PMID 41409610, 2025). "However, as shown in our study, vitamin D deficiency may worsen this condition as it decreases the availability of vitamin D to bind to the VDR and regulate serotonin and melatonin synthesis." (PMID 38584183, 2024). "Hence, it is plausible to hypothesize that this polymorphism in VDR may yield functional consequences similar to those observed in vitamin D deficiency, suggesting a potential link to poor sleep quality." (PMID 38584183, 2024).
vitamin D deficiency (continued). "Skeletal muscle oxidative stress, which impacts mitochondrial activity and contributes to the development of skeletal muscular atrophy, is linked to vitamin D deficiency (low serum of 25-Hydroxyvitamin D: 25(OH)D), and the activation of VDR may be associated with these detrimental effects." (PMID 39599698, 2024). "Specifically, the vitamin D receptor (VDR)‐driven response occurs with the concomitant inhibition of inflammatory T cells, favouring tolerogenic phenotypes, whereas vitamin D deficiency may lead to dysregulation of T‐cell function and increase the risk of autoimmune disorders." (PMID 38500390, 2024). "Therefore, it may be postulated that this alteration in the VDR protein can result in functional consequences similar to those of vitamin D deficiency." (PMID 38519539, 2024). "Likewise, it has been also reported that vitamin D deficiency would lead to dysregulation of VDR." (PMID 37410265, 2024). "Given the estimated high prevalence of vitamin D deficiency among Malaysian pregnant women, we hypothesized that there are sequence variants in the BsmI and FokI VDR gene fragments (as the most common genotypes associated with HDP) of Malaysian pregnant women with vitamin D deficiency." (PMID 38530345, 2024). "In addition, vitamin D receptor activity might be correlated with aldosterone excess in PA and interfere with secondary hyperparathyroidism; thus, vitamin D deficiency should be adequately replaced." (PMID 38139166, 2023). "Reduced serum levels of active vitamin D may be attributed to malnutrition, particularly in Sub-Saharan Africa, where even 50.06% of apparently healthy children experience vitamin D deficiency, but also to vitamin D receptor (VDR) gene polymorphisms, liver and renal failure, and estrogen deficiency." (PMID 36826156, 2023). "Thus, we speculated that vitamin D deficiency might induce myocardial fibrosis by inhibiting VDR, activating the TGF-β1-Smad2/3 pathway, and inducing inflammatory infiltration." (PMID 36771445, 2023). "Thus, regulation of hepcidin-ferroportin axis in retinal EC through VDR could play an important role in the regulation of ocular iron homeostasis and oxidative stress, and the vascular dysfunction associated with vitamin D deficiency." (PMID 36672270, 2023). "Therefore, VDR polymorphisms might explain why vitamin D deficiency is more frequently present in some T2DM patients." (PMID 36839157, 2023). "Animal studies have also shown that vitamin D deficiency might play a role in primary tumor growth and the development of metastases in breast cancer cells, and an association between low vitamin D receptor expression and occurrence of more aggressive breast cancer has been seen." (PMID 36986179, 2023). "In this study, by hypothesizing a convergence of signaling, we uncovered a novel ERRα/VDR axis through which ERRα promoted a putative mechanism of vitamin D deficiency and deregulation of VDR genomic action by activating estrogen signaling in breast cancer cell lines." (PMID 34003583, 2022). "This study showed a high prevalence of vitamin D deficiency/insufficiency in this South African population, with decreased vitamin D levels observed in hyperglycaemic individuals, which was not linked to either vitamin D-binding protein or polymorphisms in Fok1 of the VDR gene." (PMID 35956323, 2022). "In animal studies, VDR knockout mice had small and variable muscle fibres; vitamin D deficiency in rats inhibited mammalian target of rapamycin complex 1 (mTORC1) signalling and contributed to decreased protein synthesis in skeletal muscles, while VDR overexpression induced muscle hypertrophy." (PMID 35147511, 2022). "However, whether vitamin D deficiency would result in some impacts on the vitamin D binding receptor (VDR) remains to be characterized in AD." (PMID 34725922, 2021). "Third, VDR ablation and vitamin D deficiency may increase the myostatin levels." (PMID 34070910, 2021).
vitamin D deficiency (continued). "Moreover, an association between adiposity phenotypes and vitamin D receptor (VDR) gene polymorphisms has been implied in numerous studies.Therefore, vitamin D deficiency could result in fat augmentation which deteriorated clinical status of obesity." (PMID 33473294, 2021). "Consequently, vitamin D deficiency could reduce the effectiveness of the IFN-mediated antiviral response due to higher levels of unbound VDR." (PMID 34827621, 2021). "In addition, adequate levels of serum vitamin D are required to protect against bone fracture and that the complications of vitamin D deficiency particularly the vitamin D status and mutations in the vitamin D receptor markedly contribute to bone health among elderly women." (PMID 34938374, 2021). "Moreover, vitamin D deficiency has been reported to be positively associated with thyroid cancer through the increased expression of p27, known as a tumor suppressor protein, by binding to the vitamin D receptor." (PMID 33946728, 2021). "Thus, the low stimulation of VDR at the mitochondrial level in people with vitamin D deficiency may provoke mitochondrial dysfunction, an increased oxidative stress and, consequently, cell death." (PMID 32967329, 2020). "However, allelic variants of vitamin D receptor (VDR) and VDREs in different human populations may determine the threshold for vitamin D deficiency and thus risk for MS." (PMID 33304315, 2020). "Moreover, it is shown that vitamin D deficiency may induce paraspinal muscle atrophy and decreases the concentration of intramyonucelar VDR and gene expression of VDR." (PMID 30830277, 2019). "Therefore, a further study to investigate the influence of vitamin D deficiency on muscle mitochondrial biogenesis in a way of using VDR genetic modification or vitamin D-depleted diet may be warranted." (PMID 31744213, 2019). "Therefore, the increased VDR turnover induced by low vitamin D levels may aggravate the adverse cellular effects of vitamin D deficiency." (PMID 30796319, 2019). "Moreover, it remains unclear whether it is Vitamin D deficiency and VDR that contributes to obesity or is it obesity that causes low Vitamin D levels as adipose tissue has been shown to sequester Vitamin D leading to reduced plasma levels." (PMID 29343214, 2018). "The vitamin D receptor (VDR) plays a vital role in mediating the effects of the biologically active form of vitamin D (1, 25, OH-D); therefore it is plausible that variations in these receptors will modulate the consequences associated with vitamin D deficiency." (PMID 29415666, 2018). "Hypotheses linking developmental vitamin D deficiency and altered brain development are biologically plausible, since the vitamin D receptor (VDR) is expressed in the brain, particularly in areas of interest to schizophrenia research such as dopaminergic-rich brain regions." (PMID 30523285, 2018). "As 1,25(OH)2D3 treatment suppresses cancer cell growth in vitro, and vitamin D deficiency enhances breast and prostate cancer growth in animal models of bone metastasis, we hypothesized that ablation of the VDR in human breast cancer cells would promote tumor growth." (PMID 28944088, 2017). "Hence, in a ligand-depleted context (that is, vitamin D deficiency), the unliganded VDR may be responsible for increased breast cancer cell growth." (PMID 28944088, 2017). "Thus, despite displaying generalized fiber atrophy, the VDR−/− mouse model might offer insights into identifying mechanisms that promote fiber-type-specific atrophy during vitamin D deficiency." (PMID 28122601, 2017). "Thus, in the case of vitamin D deficiency, cancer cells may lose the ligand-mediated nuclear signaling effects of the VDR and as a consequence, the unliganded VDR may become the dominant functional form." (PMID 28944088, 2017).
vitamin D deficiency (continued). "Sufficient vitamin D can increase vitamin D receptor levels to produce antimicrobial peptides through the toll-like receptor pathway, while vitamin D deficiency could increase susceptibility to infection by impairing the induction of antimicrobial peptides in the same way." (PMID 27213444, 2016). "Thus, in the presence of general vitamin D deficiency in our patients and controls, there is a possibility that other interacting factors including polymorphism in vitamin D receptor genes might play a key role in developing MS." (PMID 26056552, 2015). "Thus, increases in body fat mass could worsen the state of vitamin D deficiency, which may further increase body fat mass through vitamin D receptor regulation of pathways that are yet to be confirmed." (PMID 22958612, 2012). "The BsmI, ApaI and TaqI wild variants of the VDR gene, as well as the GGT haplotype, were associated with lower vitamin D levels, suggesting that VDR gene polymorphisms could be linked to higher susceptibility to vitamin D deficiency in a sub-population of children and adolescents." (PMID 22681928, 2012). "Therefore, it is possible to hypothesize that the VDR genotype influences the susceptibility to vitamin D deficiency in children and adolescents." (PMID 22681928, 2012). "A recent review indicates that vitamin D deficiency may predispose to glucose intolerance, altered insulin secretion and type 2 diabetes, either through a direct action via vitamin D receptor (VDR) activation or indirectly via calcemic hormones and also via inflammation." (PMID 22347618, 2012). "Previous studies have indicated that activation of the VDR in both liver and macrophage cell lines resulted in decreased levels of CHOP, NF-κB p65, and inflammatory cytokines, whereas vitamin D deficiency diminished these beneficial effects." (PMID 38732118, 2024). "Recent studies have uncovered a paradoxical finding in CKD, where vitamin D deficiency is accompanied by overexpression of fibroblast growth factor-23 (FGF-23), despite FGF23 levels being regulated by the calcitriol-activated vitamin D receptor (VDR)." (PMID 38732588, 2024). "Although with a higher prevalence of vitamin D deficiency, up-regulation of miR-346 and TNF-α and down-regulation of vitamin D receptor were reported to be responsible for the induction of apoptosis in oral mucosal keratinocytes in OLP patients." (PMID 38907640, 2024). "Vitamin D deficiency (VDD) and vitamin D receptor knockout (VDR KO) have been found to reduce corneal nerve density in diabetic mice." (PMID 38136625, 2023). "Vitamin D insufficiency and deficiency are associated with an increased risk of IBD in humans, and polymorphisms in the VDR gene are associated with IBD susceptibility." (PMID 36834927, 2023). "We observed that the genotypes rs2282679-AA and rs7975232-AA, associated with vitamin D deficiency (VDD) and the vitamin D receptor (VDR), respectively, were the most prevalent in our study." (PMID 37834314, 2023). "Vitamin D deficiency is associated with the onset and activity of IBD, mainly because vitamin D exerts a regulatory role in mucosal immunity and host defenses via VDR." (PMID 36364726, 2022). "VDR activation by LCA decreases vitamin D signaling and induces vitamin D insufficiency or deficiency by inducing vitamin D catabolism." (PMID 36590590, 2022). "Furthermore, it has been reported that vitamin D deficiency may induce paraspinal muscle atrophy and reduction in intramyonuclear VDR concentrations and VDR gene expression, while vitamin D plays a key role in the regulation of mitochondrial oxygen consumption and dynamics." (PMID 35565827, 2022). "Although the results of studies on the role of vitamin D deficiency in the severity of COVID-19 are ambiguous, it has been shown that SARS-CoV-2 infection can inhibit the activity of the vitamin D receptor." (PMID 34557267, 2021).
vitamin D deficiency (continued). "Given the presence of high levels of VDR in the brain, and also based on the fact that 1,25D3 doses used in our study may reflect the range of concentrations to which microglia would likely be exposed, it is reasonable that vitamin D deficiency may directly affect microglia functioning." (PMID 33808491, 2021). "Vitamin D deficiency has adverse effects on renal allograft outcomes, and polymorphisms of genes encoding vitamin D-binding protein (VDBP) and vitamin D receptor (VDR) are defined to play a role in these conditions." (PMID 33801744, 2021). "It has also been observed that in different diseases (renal, hepatic, cardiovascular, dermal, etc.), the deletion of VDR or vitamin D insufficiency promotes the increase in oxidative stress." (PMID 32967329, 2020). "One SNV (rs59128934) on VDR and another (rs3886163) on CYP24A1 were associated with increased risk to Vitamin D deficiency." (PMID 32834827, 2020). "Vitamin D deficiency (VDD) and VDR gene polymorphisms are associated with an increased risk for the development of TB." (PMID 32521634, 2020). "Evidence has also shown that Vitamin D deficiency (VDD) and Vitamin D receptor (VDR) polymorphisms are associated with tuberculosis (TB)." (PMID 32521634, 2020). "T1D-induced vitamin D deficiency is associated with impairments of renal and extrarenal CYP27B1 and VDR expression." (PMID 29552033, 2018). "Previous studies indicated that vitamin D supplementation in the elderly with vitamin D insufficiency reduced an atrophy of type II muscle fiber and increased the size of type I and II muscle fiber, as well as VDR concentration." (PMID 28933742, 2017). "Based on previous studies that vitamin D deficiency promotes breast cancer growth in bone as well as the known anti-proliferative effects of vitamin D on breast cancer cells, we originally hypothesized that knockdown of the VDR in breast cancer cells would promote tumor cell growth." (PMID 28460457, 2017). "Recently, the role of vitamin D receptor (VDR) in NAFLD has been investigated; evidence showed that vitamin D deficiency contributes to the development of NAFLD; vitamin D levels are related to the histological severity of steatosis." (PMID 27642591, 2016). "Attempting to establish a link between fibrosis formation and vitamin D deficiency, we evaluated the expressions of TGF-β and VDR in IRI and VDD+IRI groups, both with more prominent interstitial expansion." (PMID 25222475, 2014). "Albeit the question on whether VDR exists in fully differentiated muscle or plays its pivotal role in myogenesis still is to be clarified, it is undeniable that vitamin D supplementation ameliorates proximal myopathy and muscle pain in patients with severe vitamin D deficiency." (PMID 24895631, 2014). "In our study, we found reduced expression of VDR and increased expression of TGF-β in VDD+IRI group, supporting the idea that vitamin D deficiency is associated with tubulointerstitial damage and interstitial fibrosis." (PMID 25222475, 2014). "Expression of VDR and TNF-α and the effect of vitamin D deficiency in post-angioplasty coronary arteries were analyzed by immunohistochemistry and histomorphometry." (PMID 22880111, 2012). "Recent data from vitamin D receptor knockout (VDR−/−) mice, an animal model that emulates vitamin D deficiency, revealed a far greater number of fibrotic lesions in the hearts of these mice compared to those of the wild-type mice." (PMID 22536373, 2012). "Furthermore, we speculate that some of the toxic effects induced by Aβ, including disruption of calcium homeostasis and dysregulation of NGF synthesis, may be caused by vitamin D deficiency and/or the inefficient utilization of vitamin D due to VDR protein depletion." (PMID 21408608, 2011). "For the COVID-19 patients, we performed a comparative statistical analysis between those with vitamin D deficiency (≤20 ng/mL) and those without (>20 ng/mL) in relation to their comorbidities and VDR polymorphisms." (PMID 41301713, 2025).